ZC3H12A (zinc finger CCCH-type containing 12A)
Diseases named in the same sentence as ZC3H12A in open-access papers (continued):
Sharing a sentence is not in itself a finding about the gene and the disease.
Peritoneal Fibrosis (1 paper, 2019). Disorder characterized by a wide range of structural changes in PERITONEUM, resulting from fibrogenic or inflammatory processes. "Whereas the role of TNFAIP6 and ZC3H12A in peritoneal fibrosis have not been reported yet, superoxide dismutase 2 encoded by SOD2 is a mitochondrial antioxidant previously known to play a role in protection against peritoneal fibrosis." (PMID 30728376, 2019).
primary biliary cholangitis (1 paper, 2024). Primary biliary cholangitis (PBC) is a chronic and slowly progressive cholestatic liver disease of autoimmune etiology characterized by injury of the intrahepatic bile ducts that may eventually lead to liver failure. "In addition, mice with liver-specific deletion of Zc3h12a develop features of primary biliary cholangitis." (PMID 38311169, 2024).
vitiligo (1 paper, 2024). Generalized well circumscribed patches of leukoderma that are generally distributed over symmetric body locations and is due to autoimmune destruction of melanocytes. "Cluster12 keratinocyte RBP-expression groups, namely, ZC3H12A, S100A9, CYCS, and EIF5A, were also enriched in the apoptotic pathway in the patients with vitiligo." (PMID 38438962, 2024).
tumor (68 papers, 2012 to 2026). "REGNASE-1 is a major negative regulator of anti-tumor response mediated by T cells which are encoded by the Regnase 1 gene (also known as zc3h12a) with having RNA degrading properties)." (PMID 36109471, 2023). "More specifically, the activation of NF-kB in tumor cells enhances the expression of several genes (including Ccl7, Cxcl1, Ccl5, Slc39a10, Lcn2, Zc3h12a, and Enpp2) that are implicated in tumor migration, angiogenesis, and formation of pre-metastatic niches." (PMID 33567747, 2021). "Our results also showed that patients with lower ZC3H12A gene expression had more aggressive tumor features and that lower ZC3H12A expression was associated with significantly shorter disease-free survival." (PMID 31106233, 2019). "The association of ZC3H12A expression with CRC tumor stage should be validated in large prospective trials before it can be translated into clinical practice." (PMID 31106233, 2019). "Consistent with its tumor stage association, patients with lower ZC3H12A expression also had more aggressive tumor features in the TCGA CRC cohort, including tumor pathologic T stage (P = 0.0005), residual tumor (P = 0.033), distant metastasis (P = 0.044) and positive lymph nodes (P = 0.0008)." (PMID 31106233, 2019). "As a pivotal molecular node, the functional state of ZC3H12A directly determines the equilibrium of the tumor ecosystem." (PMID 41154702, 2025). "In recent years, ZC3H12A has emerged as a critical target for tumor immunotherapy, particularly CAR-T cell therapy." (PMID 41154702, 2025). "In most cancers, ZC3H12A exerts potent tumor suppressing effects by targeting key signaling pathways." (PMID 41154702, 2025). "ZC3H12A contributes to antitumor immunity and influences multiple biological properties of tumor cells." (PMID 41154702, 2025). "ZC3H12A exhibits highly context-dependent roles in cancer biology, functioning as either a tumor suppressor or an oncogene depending on the specific cellular signaling environment." (PMID 41154702, 2025). "On the other hand, the tumor microenvironment also actively participates in attacking ZC3H12A: M2 macrophages deliver miR-143-3p to cancer cells via secreted extracellular vesicles." (PMID 41154702, 2025). "Despite T cells rarely infiltrating tumor lesions, a notable presence of CD8+ T cells was observed near the lymph nodes of the C1 tumor, potentially due to enhanced recruitment facilitated by Zc3h12a-specific sgRNA enrichment." (PMID 39605490, 2024). "The coordinate correlation of ZC3H12A expression levels with tumor stage and prognosis presented in this study provides a potential mechanism underlying that chromosomal association." (PMID 31106233, 2019). "In support of these findings, we further found that patients with lower ZC3H12A expression had more aggressive tumor features and shorter disease-free survival." (PMID 31106233, 2019). "Similarly, in breast cancer, ZC3H12A inactivates IL-17 signaling to suppress tumor growth and metastasis and exerts anti-proliferative effects by inducing G0/G1 cell cycle arrest in triple-negative breast cancer (TNBC)." (PMID 41154702, 2025). "Dysfunction of ZC3H12A profoundly reshapes the entire tumor ecosystem." (PMID 41154702, 2025). "This review systematically summarizes the multifunctional roles of ZC3H12A in immune regulation, tumor therapy, metabolic disorders and inflammation-related diseases, with the aim of providing new insights into its potential application in the treatment of human diseases." (PMID 41154702, 2025). "Across multiple CAR-T platforms—including CD19, GD2, and others—simultaneous knockout of ZC3H12A and BCOR induces the generation of functionally distinct “tumor-immunological fitness” (TIF) T cells." (PMID 41154702, 2025). "In gliomas, ZC3H12A promotes angiogenesis through VEGFA-mediated ERK activation, demonstrating pro-tumor activity." (PMID 41154702, 2025).
tumor (continued). "Tumour suppressor genes expression levels (APOL1, TP53INP1 and ZC3H12A) were low in BLCA tissues comparing with normal bladder." (PMID 33960661, 2021). "In summary, ZC3H12A is elevated in stage I CRC patients and correlated with tumor prognosis likely due to its involvement in immune or inflammatory process." (PMID 31106233, 2019). "Research indicates that knocking out ZC3H12A reprograms CD8+ T cells into a unique “long-lived effector” state, significantly enhancing their accumulation, persistent survival, and killing capacity at tumor sites." (PMID 41154702, 2025). "Although for genes like Il15 we did not observe any difference between healthy and tumor-bearing mice in Ficoll or Parsortix samples; others, such as Egr1, Zc3h12a, Klf4, or Nfat5, allowed distinguishing for cancer or CTC presence." (PMID 35153760, 2021). "Similarly, knockout of Regnase-1 (ZC3H12A), a regulator of cholesterol metabolism and immune signaling, reprograms T cells into long-lived effector cells with enhanced persistence, metabolic fitness, and anti-tumor function." (PMID 41463143, 2025). "Furthermore, multivariate Cox proportional hazards model analyses showed that ZC3H12A expression was significantly correlated with survival independent of patient sex and age, but not of tumor stage." (PMID 31106233, 2019).
cancer (42 papers, 2013 to 2026). A tumor composed of atypical neoplastic, often pleomorphic cells that invade other tissues. "By targeting and inhibiting ZC3H12A, they release its suppression of the transcription factor C/EBPβ, thereby activating pro-cancer signaling and promoting CRC progression." (PMID 41154702, 2025). "Targeting Zinc finger CCCH-type containing 12A (ZC3H12A), which encodes the ribonuclease REGNASE-1 was revealed to program long-lived effector T cells for cancer therapy by screening with a metabolic library targeting 3,017 genes." (PMID 38162677, 2023). "Beyond the well-studied genes, our data indicated the potential roles of several other genes, including PAQR5, TRIM16, and ZC3H12A, in modulating cancer cell behavior." (PMID 37958599, 2023). "Recurrent mutations in PIGR and ZC3H12A are of particular interest because these have not been described in cancer but have roles in immunoregulation and reflect distinct mechanisms of positive selection in the IBD colon." (PMID 32697969, 2020).
infection (23 papers, 2014 to 2026). The state of being infected such as from the introduction of a foreign agent such as serum, vaccine, antigenic substance or organism. "The data indicated that the upregulated expression of lipid metabolism-related genes, such as PLPP3 and ZC3H12A, occurred as early as 5 h post-infection." (PMID 39872814, 2024). "We found that Tristetraprolin (TTP), Nocturnin (NOCT or CCR4NL), and Zinc Finger CCCH-Type Containing 12A (ZC3H12A or Regnase-1) were all up-regulated during the infection." (PMID 35573800, 2022). "Further genes pointing towards NF-κB signalling during infection, such as il1b, il23a, nfκbia, tcim and zc3h12a, were also found to be induced by the bacteria in this study in presence or absence of the Erk1/2 inhibitor." (PMID 34863201, 2021). "The minimal effect of anti-IL-17A treatment on Ccl2 and rather a slightly decreased gene expression of Zc3h12a in lung tissue at day 28, suggest a dispensable role for IL-17A at this stage of the infection." (PMID 27853279, 2016). "Noteworthy, we observed induction of the Zc3H12a gene, whose product acts as an RNAse and can degrade mRNA encoding for IL6, in HIBCPP cells after infection with the MC58 strain." (PMID 25347003, 2014). "Moreover, the splenic expressions of zc3h12a and irf7 predicted to be targeted by ssa-miR-146a-5p and nbr-miR-731, respectively, were also significantly affected by infection; particularly, the zc3h12a showed significantly higher expression at 6 h after infection than the control." (PMID 36059498, 2022). "In addition to the cytokine and chemokine upregulation observed in this present work, the inflammatory response regulators SLAMF7, RELB, NFKBIZ, NFKBIA, and ZC3H12A were identified, further underlining the strong inflammatory response elicited by PCPEC during to infection." (PMID 33763387, 2021). "The upregulated expression of the C3 and ZC3H12A genes and upregulated expression of antiviral genes, such as CXCL8 and NEURL3, occurred at 9 h post-infection." (PMID 39872814, 2024). "For the validation of the data obtained for gene expression after infection with the NmB and NmC strains in presence and absence of the capsule, il6, il8, nfkbiz, zc3h12a and tnf were chosen." (PMID 34863201, 2021).
immune diseases (2 papers, 2021). "ZC3H12A is an essential RNase that prevents immune disorders by directly controlling the stability of a group of inflammatory genes." (PMID 34880865, 2021).
infectious disease (1 paper, 2025). A disorder directly resulting from the presence and activity of a microbial, viral, or parasitic agent in humans. "Furthermore, ZC3H12A plays a crucial role in systemic metabolic–immune crosstalk and infectious diseases." (PMID 41154702, 2025).
ZC3H12A also shares sentences with these, for which no sentence is quoted: diabetes (10 papers); Autoimmunity (9); ischemic stroke (8); neuroblastoma (8); Cerebral ischemia (7); clear cell renal cell carcinoma (7); Splenomegaly (7); ischemia (6); pancreatic cancer (6); pancreatitis (6); Sepsis (6); heart failure (5); Stroke (5); hepatocellular carcinoma (4); myocardial infarction (4); systemic lupus erythematosus (4); brain injury (3); experimental autoimmune encephalomyelitis (3); glioma (3); inflammatory bowel disease (3); Lymphadenopathy (3); melanoma (3); multiple myeloma (3); Obesity (3); osteosarcoma (3); periodontitis (3); squamous cell carcinoma (3); type 2 diabetes (3); acute respiratory distress syndrome (2); anemia (2).
A further 96 diseases each share a sentence with ZC3H12A in 2 papers or fewer.